MYD88 (MYD88 innate immune signal transduction adaptor)
Diseases named in the same sentence as MYD88 in open-access papers (continued):
Sharing a sentence is not in itself a finding about the gene and the disease.
infection (continued). "MyD88 deficient mice infected with either R. conorri or R. australis were more susceptible to infection than WT mice, suggesting a protective role of MyD88 in the immune response against SFG Rickettsiae." (PMID 31134081, 2019). "Immune and endothelial cells, as well as hematopoietic stem cells, express TLRs, and the hyperactivation of MyD88 during infection is associated with hematopoietic diseases as well as a number of inflammatory disorders." (PMID 30642901, 2019). "Similar to what was observed after intraperitoneal infection, Myd88+/− and Myd88+/+ mice experienced a transient and moderate loss in weight with a nadir at d2 post intratracheal infection, but regained weight within 1 week." (PMID 30800124, 2019). "Here, we have used MyD88-deficient mice to investigate the course of infection with the attenuated NMII strain." (PMID 30800124, 2019). "Similar to wild-type BMDCs, nuclear translocation of Egr-1 was observed in MyD88-deficient BMDCs upon infection with T. gondii tachyzoites." (PMID 31681626, 2019). "Here, we have employed MyD88-deficient mice in infection models with the attenuated C. burnetii Nine Mile phase II strain (NMII)." (PMID 30800124, 2019). "For instance, C57Bl/6 MyD88-null mice are more susceptible to infection with L. major than wild type animals while C57BL/6J TLR2−/− mice infected with L. braziliensis are more resistant to infection than C57BL/6J wild type mice." (PMID 31119102, 2019). "This manuscript demonstrates an essential role for the TLR/IL-1R-associated adapter protein MyD88 in the control of C. burnetii replication in macrophages in vitro and for efficient local containment and elimination of the bacteria after infection in vivo." (PMID 30800124, 2019). "The role of MyD88 in host resistance and susceptibility to infections with other Rickettsial pathogens, such as Rickettsia conorii or Rickettsia australis; Spotted fever group (SFG) rickettsiae has also been examined." (PMID 31134081, 2019). "At a low challenge dose (1 to 3 50% lethal doses [LD50]), 50% of WT mice survived the infection, whereas the Myd88−/− mice were significantly more susceptible and succumbed on days 3 and 4 postinfection." (PMID 30642901, 2019). "We have previously demonstrated that MyD88−/− mice are susceptible to infection by an attenuated strain of S. typhimurium (BRD509E)." (PMID 29973931, 2018). "The importance of Myd88 in host defense following JHMV infection is emphasized in a recent report indicating that infection of Myd88-/- mice increased mortality associated with failure to control viral replication and enhanced neuropathology." (PMID 30577473, 2018). "This is in accordance with animal models of infection, which found that naive myd88−/−tlr3−/− and tlr7−/− mice were more susceptible to influenza virus infection, demonstrating that MyD88 signaling is important in resisting primary challenge." (PMID 29552008, 2018). "While one study reported that MyD88 deficiency had little effect on protection, we and others have shown that MyD88-deficient mice are profoundly susceptible to infection." (PMID 29973931, 2018). "In all cases, resident macrophage recruitment was independent of TLR-Myd88 signaling, as they were still responding toward infection in Myd88-deficient fish." (PMID 28844797, 2017). "For example, MyD88-deficiency in humans enhances the sensitivity to infection by a narrow range of mostly pyogenic bacteria, in contrast to the broad-spectrum risk of infection in MyD88 knockout mice." (PMID 28611775, 2017). "In summary, Il18r1−/− mice presented an intermediary level of susceptibility to infection with T. cruzi, in terms of survival and parasite load in the myocardium, when compared to Myd88−/− and WT (B6) mice." (PMID 28895840, 2017). "Three different autosomal recessive mutations have been described in MYD88-deficient patients suffering from recurrent infections with pyogenic bacteria." (PMID 29247242, 2017).
infection (continued). "In the absence of both TLR2 and MyD88, P. gingivalis persists in the oral cavity but is unable to induce bone loss, further confirming the essential role of TLR2-dependent, MyD88-independent inflammation in bone loss that develops in response to infection." (PMID 28848717, 2017). "Co-localization analysis revealed that about 20% of Mav were associated with MyD88 4 hours post infection, decreasing over time for live Mav and, conversely, increasing over time for PFA-killed Mav (P <0.005)." (PMID 28806745, 2017). "Myd88-deficient animals are highly susceptible to infection by multiple pathogens, including T. cruzi, and exhibit diminished Th1 differentiation, which has been attributed to defective IL-12 production by APCs, as a consequence of poor TLR signaling." (PMID 28895840, 2017). "TLR4 is reportedly not required to control acute BCG infection, and TLR4-deficient mice display reduced bacterial clearance during long-term infection depending on the types of mutation in the common adaptor protein MyD88." (PMID 28881802, 2017). "For this reason, we were interested in evaluating visible clinical manifestations of infection as well as corneal bacterial load early in the course of infection, directly comparing these parameters in MyD88- and IL-1R-deficient animals." (PMID 28796783, 2017). "When infected orally with C. rodentium, mice with a complete deficiency in MyD88 (MyDOFF mice) quickly succumbed to infection as expected." (PMID 28520792, 2017). "On the other hand, Myd88−/− mice are the most susceptible to infection, as all mice of this strain were dead by day 15 pi, while the totality of Il18r1−/− mice were dead only by day 23 pi, a time point at which only 32.5% of WT mice have succumbed." (PMID 28895840, 2017). "This would explain, in part, the increased susceptibility to injury and infection seen with MyD88 deficiency, not only in the cornea, as we demonstrate with pseudomonas keratitis, but in other tissues as well." (PMID 28796783, 2017). "MyD88 deficiency has been linked to susceptibility for invasive pneumococcal disease and infections from S. aureus and P. aeruginosa." (PMID 28127112, 2016). "MyD88 is significant for the protection against TB as evidenced by the fact that mice with a complete germline deletion of MYD88 are particularly susceptible to infection." (PMID 28127112, 2016). "More recently, it has become clear that IL-1β is also of critical importance for host control of TB infection given that mice deficient in IL-1R or its adaptor MyD88 succumb rapidly to low-dose aerosol infection with TB." (PMID 27034588, 2016). "This notion is supported by the finding that miR-K5 was upregulated during later stages of infection and that MyD88 was able to inhibit latency-associated nuclear antigen-1 (LANA-1)." (PMID 27070595, 2016). "As expected, M1 macrophage phenotype markers also decreased in MyD88-deficient BMDMs during H37Ra infections in macrophage-polarized condition." (PMID 27845414, 2016). "MyD88 deficiency enhances susceptibility to infections caused by viruses, bacteria, parasites and fungi, but its contribution to resistance varies depending upon the pathogen." (PMID 26367276, 2015). "TLRs are important in host resistance, and there is evidence that TLR2, 4, 9 and 11 are involved in recognition of T. gondii although knockout of no single TLR results in the high susceptibility observed following infection of MyD88−/− mice." (PMID 26528819, 2015). "Previous studies revealed a critical role of TLR-mediated innate immune response in protecting mice against S. pyogenes: mice deficient in MyD88 exhibited decreased survival in a subcutaneous infection model, the model we employed in this study." (PMID 25756897, 2015). "Altogether, these observations suggest that early, strong and irreversible damage is caused to secondary lymphoid organs upon infection in Ly49H-/-MyD88-/-animals." (PMID 25954804, 2015).
infection (continued). "In Myd88-deficient animals, local inflammatory responses are reduced, leading to significant spread of infection, overwhelming systemic inflammation and consequent death of the animals." (PMID 26147469, 2015). "Mice deficient in the TLR/IL-1R family receptor adaptor molecule MyD88 have been shown to be highly susceptible to infection with MTB, which suggests a major role for this pathway in the innate defense against the MTB." (PMID 25312698, 2015). "Our studies support this notion, and showed that BMDM deficient in RIP3, NLRP3, ASC, and MyD88 all had pathogen specific reductions in cytotoxicity following infection." (PMID 26659062, 2015). "Stimulation of macrophages with TLR ligands increased the expression of iNOS in vitro, and we have previously shown that a zebrafish mutant for the important TLR/IL1R signaling adaptor MyD88 (myd88−/−) was more susceptible to Mm infection." (PMID 24967596, 2014). "MyD88/STING-deficient mice had similar bacterial burdens as MyD88-deficient mice early after infection, however by day 3, had significantly higher CFU in the spleen and the liver." (PMID 24391507, 2014). "MyD88-deficient mice are highly susceptible to Francisella infection indicating PRRs are critical to the host’s immune response during infection." (PMID 25250027, 2014). "MyD88-deficient mice exhibit knee arthritis at day 45 of infection that is reduced in prevalence and severity in the absence of FcγR." (PMID 24967215, 2014). "There was a large reduction in the levels of local inflammatory mediators and recruitment of neutrophils to the infection site in MyD88-deficient compared to wild-type mice." (PMID 25084278, 2014). "As evidenced by the fact that infection with either L.g LRVhigh or L.g LRVlow parasites into the MyD88−/− or TLR9−/− mice were more susceptible than wild type controls regardless of the viral burden." (PMID 24801628, 2014). "In fact, TLR4-deficient and MyD88-deficient mice were more susceptible to infection and exhibited greater pathology than wild-type mice." (PMID 24995345, 2014). "For example, loss of either TLR2 (Toll-like receptor 2) or MyD88 results in reduced survival as a result of tularemic infection." (PMID 23349802, 2013). "Induction of miR-146a and miR-146b by infection was shown to be affected by deficiencies in Traf6 and Myd88, which are central intermediates of Toll-like receptor and cytokine signalling pathways." (PMID 24112639, 2013). "The studies presented here demonstrate that while MyD88-deficient mice are able to control the early phase of infection, they were highly susceptible to cerebral infection." (PMID 23374751, 2013). "For example, MyD88−/− mice infected with either B. pseudomallei or B. mallei were much more susceptible to infection than wild type mice." (PMID 23508691, 2013). "The NLRP3−/− and caspase-1−/− macrophages demonstrated a marked deficiency in the control of infection, as the number of amastigotes and the frequency of infected cells were even higher than in the susceptible MyD88−/− macrophages." (PMID 24098823, 2013). "We evaluated resistance to the primary infection and re-challenge in MyD88-or TRIF-deficient mice intravaginally infected with the fungus." (PMID 23853597, 2013). "Transfer of B cells from MyD88−/− mice into naive mice resulted in impaired control of infection, associated with lower IL-13 production by T cells in the mediastinal lymph node." (PMID 24204255, 2013). "The degree of type I collagen deposition was significantly increased in MyD88 KO mice at day 7 post-infection; however, type I collagen levels were similar between WT and MyD88 KO mice at day 14, again indicating an early effect of MyD88 loss." (PMID 22879997, 2012). "Similar to the results described for the spleen, systemic spread of the organism to the liver is delayed in TLR4−/− and MyD88−/− mice, and is associated with a corresponding delay in the clearance of infection." (PMID 22973560, 2012).
infection (continued). "In fact, Myd88−/− mice were shown to be highly susceptible to infection and to display lower production of proinflammatory cytokines, including IL-12p40 and IFN-γ, from innate immune cells." (PMID 22496959, 2012). "We elected to study organs at day 12 post-infection because this preceded the earliest observed mortality in this infection model, which was at day 14 post-infection in MyD88-deficient mice." (PMID 22039448, 2011). "On the other hand, B-cells lacking Myd88 or TLR2 -in contrast to wild type B-cells- were incapable of preventing the characteristic infection-associated immunopathology of Myd88-/- or IL-10-/- strains when adoptively co-transferred with Tr1 cells." (PMID 22044597, 2011). "In this regard, our data cannot exclude the role of other TLRs (which also signal through MyD88 such as TLR2) in the regulation of apoptosis upon infection with the pathogenic meningococcal isolates." (PMID 22144896, 2011). "In vivo, iNOS-levels were considerably reduced in MyD88-deficient mice post infection with C. pneumoniae." (PMID 22096480, 2011). "In agreement with the data presented here, infection of MyD88-deficient mice with Mycobacterium bovis BCG also triggered CD4+ T-cells to produce IFNγ." (PMID 22096480, 2011). "As conventional housed mice are not susceptible to C. difficile infection, we evaluated if the intestinal alterations in TLR4−/− and MyD88−/− mice rendered these mice innately more susceptible to infection." (PMID 21738466, 2011). "Further experiments showed the bba64 mutant was not culturable from mouse skin taken at the nymphal bite site and was unable to establish infection in MyD88-deficient mice via tick infestation." (PMID 21559293, 2011). "We found that infection of mu-cDCs isolated from mice double deficient in MyD88 and TLR3 with the KOS strain of HSV-1 responded identically to mu-cDCs from wild-type control mice." (PMID 20174621, 2010). "In contrast, MyD88-deficient mice had significantly increased bacterial loads at both day 10 and 14 post infection." (PMID 20668698, 2010). "Mice deficient in MyD88, the adaptor molecule required for signaling events by most TLRs as well as IL-1R and IL-18R, show greatly enhanced susceptibility to infection with this protozoan parasite." (PMID 20442858, 2010). "Consistently, experiments performed in our laboratory and elsewhere demonstrate that despite of severe impairment IL-12 production in MyD88−/− mice, IFNγ is still produced at 8 days post-infection, and yet, mice are highly susceptible to ME-49 infection." (PMID 20865117, 2010). "Macroscopically, lymphoid follicles in wild-type mice were smaller and markedly irregular in shape compared to MyD88-deficient mice after infection." (PMID 20668698, 2010). "As for T. cruzi, multiple TLR ligands were identified in T. gondii and Myd88−/− mice were shown to be highly susceptible to infection." (PMID 20442858, 2010). "While very susceptible, we found that upon infection with T. gondii the double MyD88/TRIF deficient mice were somewhat more resistant than the 3d mice." (PMID 20865117, 2010). "Our results also suggest that TLR2 is not the sole MyD88-dependent receptor implicated in the antiviral response against the virus since MyD88−/− mice were highly susceptible to infection." (PMID 21060793, 2010). "We analyzed the induction of IFN-γ and cytotoxic activity in vivo in TLR2-, TLR4-, TLR9- or MyD88-deficient mice during infection, and found intact responses compared to WT mice." (PMID 20442858, 2010). "MyD88 has been associated with a protective effect during infection with Trypanosoma and Toxoplasma strains." (PMID 19432955, 2009). "Days 2, 3, 4 and 6 post infection, virus titers are significantly lower in WT mice as compared to MyD88−/− animals and these data are supported by the dramatic loss of in situ hybridization signal in WT mice by 3 dpi." (PMID 19079579, 2008).
infection (continued). "Intranasal infection of MyD88-deficient mice with RSV or VSV produces more severe disease that was correlated with a failure to recruit immune cells to the sites of infection." (PMID 19079579, 2008). "Considering this and the observed increased bacterial loads in the liver, we examined the influence of MyD88 deficiency on liver damage 72 h post infection." (PMID 18946505, 2008). "We generated myd88- or tlr4-deficient T24/83 cells to explore whether the infection triggers cytokine secretion via this signaling cascade." (PMID 41310197, 2025). "The host induction of the innate immune response at the onset of infection is mediated and controlled by intracellular signaling cascades via the recruitment of MyD88 and its association with the MyD88 adaptor-like (Mal, also known as TIR-containing adaptor protein or TIRAP)." (PMID 39125989, 2024). "Mice selectively deficient for MyD88 in lung epithelial cells were more susceptible to acute P. aeruginosa infection, with reduced recruitment of neutrophils and impaired early bacterial control post-infection." (PMID 39015565, 2024). "To further investigate the role Toll signaling is playing in creating a primed response to E. faecalis, we assayed infection response in flies with a Myd88 mutation that eliminates intracellular Toll signaling and a spz mutant that eliminates extracellular Toll signaling." (PMID 37566589, 2023). "Considering that Dram1 is a downstream target of the Tlr-Myd88-NF-κB signaling pathway, we also investigated if Dram1 could rescue the infection susceptibility of myd88 mutants." (PMID 38264729, 2023). "Thus, the drivers of infection-associated B-ALLs are similar in both Pax5+/−;Myd88+/− and Pax5+/− leukemic cells." (PMID 37620322, 2023). "Similarly, loss of the MyD88 adapter for TLR2, such as with infection in Myd88 knockout mice, also diminishes inflammatory phenotype without affecting bacterial loads." (PMID 37228668, 2023). "Thus, transcriptomic analysis demonstrated that the MyD88/IRAK-4–deficient patients were able to mount a systemic inflammatory response during the acute phase of the infection." (PMID 36880831, 2023). "However, the mechanism of susceptibility is dependent on parasite strains, while MyD88‐/‐ C57BL/6 mice infected with L. major IR75 strains show an increased susceptibility to infection as a consequence of non‐protective TH2 response." (PMID 35119120, 2022). "Cytokine levels decreased during biofilm device infection of mice deficient on MyD88." (PMID 35093033, 2022). "The inducible expression of MyD88 by V. harveyi suggested that the linker molecule MyD88 in innate immune response may play together with NaPRPS1 to coordinate the immune signaling in yellow drum in response to the pathogenic infection." (PMID 35742917, 2022). "Additionally, we reported reduced Neu1 during L. donovani-infection enhanced sialylation on TLR4 preventing its association with MyD88 resulting in an inappropriate cellular activation." (PMID 33763070, 2021). "However, a second study of MyD88 -/- mice reported instead that MyD88 loss impaired MHV68 infection, perhaps due to a role for MyD88 in B cell activation." (PMID 34749760, 2021). "Because TLR ligands can promote monocyte egress from the bone marrow to sites of infection, we evaluated neutrophil and monocyte recruitment to the dLN of mice deficient in MyD88, the canonical adaptor for many TLRs and the interleukin-1 receptor (IL-1R) family." (PMID 31999809, 2020). "Furthermore, in Hydra, MyD88-deficient polyps were more susceptible to infection with the human pathogen Pseudomonas aeruginosa." (PMID 33167855, 2020). "Furthermore, TLR2- and MyD88-deficient mice developed increased bacterial burden after intratracheal infection with C. burnetii." (PMID 30800124, 2019).